CD36 (CD36 molecule (CD36 blood group))
Diseases named in the same sentence as CD36 in open-access papers (continued):
Sharing a sentence is not in itself a finding about the gene and the disease.
Hepatic steatosis (continued). "Rather, hepatic steatosis occurs through increased NEFA flow from the diet or adipose tissue and heightened uptake by the liver, facilitated by the elevated levels of fatty acid transporters CD36 and FABP4, as shown here." (PMID 33746771, 2021). "However, GSPE treatment remarkably reduced lipid accumulation and CD36 and FABP4 expression in the liver of PFOS-exposed mice, suggesting that GSPE can reverse hepatic steatosis through modulating lipid metabolism." (PMID 33457418, 2020). "Knockdown of FATP2, FATP5, or CD36 leads to decrease of hepatic FFA uptake and ameliorates hepatic steatosis in mice, supporting the fundamental importance of FATPs and CD36 to hepatic steatosis." (PMID 32225108, 2020). "Unlike the adipocytes, CD36 expression is low at the basal level in normal hepatocytes and hepatocellular carcinoma cell lines but can be induced with lipid-rich diets or in hepatic steatosis models." (PMID 31968655, 2020). "Previously, we reported that JMJD2B enhances PPARγ2 expression by removing the repressive histone marks H3K9me2 and H3K9me3 in the promoter of PPARγ2, stimulating the expression of PPARγ2 and its steatosis target genes such as CD36 and FABP, resulting in the development of hepatic steatosis." (PMID 33167594, 2020). "Elafin overexpression also failed to inhibit liver steatosis and hepatic Cd36 mRNA expression in the HCD-treated mice." (PMID 32733043, 2020). "Interestingly, circulating levels of a soluble form of CD36 (sCD36) are abnormally elevated in NAFLD patients and positively correlate with the histological grade of hepatic steatosis." (PMID 32978374, 2020). "A study reported that the absence of CD36 in the liver remarkably retarded the development of hepatic steatosis, although FA level increased." (PMID 32733940, 2020). "CD36 mediates FFA uptake in various tissues, and FA uptake has a significant role in hepatic steatosis; thus, abnormalities in CD36 may lead to hepatic steatosis." (PMID 32733940, 2020). "JMJD2B upregulated the expression of peroxisome proliferator-activated receptor γ2 (PPARγ2) and its steatosis target genes including CD36 and fatty acid-binding protein (FABP), which are necessary for fatty acid uptake, thus resulting in the development of hepatic steatosis." (PMID 33167594, 2020). "The results of this study indicate that β3-AR stimulation can inhibit the expression of CD36 in the livers of NAFLD rats, which may be one of the mechanisms by which β3-AR helps ameliorate liver steatosis." (PMID 32503411, 2020). "Moreover, NAFLD and NASH patients show CD36 and NASH patients exhibit FATP2 and 5 gene upregulation in the liver, suggesting that these transporters contribute to hepatic steatosis and progression of fibrosis." (PMID 31771244, 2019). "In human primary hepatocytes, CD36 was hypomethylated and upregulated after 5 days of valproic acid (VPA) exposure, a HDAC inhibitor, which can also modulate the expression and DNA methylation level of genes involved in liver steatosis." (PMID 31379931, 2019). "While IHTG levels were significantly increased in the CR‐MF diet switch group, cluster of differentiation 36 (Cd36), a key fatty acid transporter in the development of hepatic steatosis, did not follow the same pattern." (PMID 29266667, 2018). "In the present study, interplay between (FAT)/CD36 and CPT-1, both higher expressed in treated groups, guarantees the maximum oxidative activity within hepatic mitochondria, enhancing fatty acid metabolization and, thus, reducing hepatic steatosis." (PMID 23700465, 2013). "In addition, fatty acid translocase/CD36 was also reduced in liver, consistent with improved hepatic steatosis." (PMID 22870290, 2012). "Therefore, upregulation of Cd36 at low dietary trans-10, cis-12-CLA is part of the mechanism leading to increased hepatic fatty acid uptake and hepatic steatosis." (PMID 22988513, 2012).
Hepatic steatosis (continued). "Thus, the released prolactin in mice consuming a high‐fat diet (HFD) can mitigate hepatic steatosis through its interaction with the hepatic prolactin receptor (PRLR) and by modulating the expression of CD36, a pivotal fatty acid translocase (FAT) of free fatty acid (FFA) uptake." (PMID 40586298, 2025). "Moreover, it could be demonstrated that CD36 expression is upregulated in the livers of MASLD patients, leading to hepatic triglyceride accumulation and consequently an exacerbation of hepatic steatosis." (PMID 40261813, 2025). "Moreover, Curc-mPEG454 reversed HFD-induced hepatic steatosis and hypertriglyceridemia by modulating the hepatic CREB/PPARγ/cluster of differentiation 36 (CD36) pathway through the activation of CREB phosphorylation and inhibition of PPARγ and CD36 expression." (PMID 37762669, 2023). "In rodents, PFAAs-induced liver steatosis and toxicity have been mainly attributed to PPARα, which activation leads to increased expression of genes involved in FAO, lipogenesis (Srebf1, sterol regulatory element-binding transcription factor 1; Fasn, fatty acid synthase), and lipid uptake (Cd36)." (PMID 37242221, 2023). "In addition, CD36 has the ability to engage with insulin-induced gene-2, enhance the production of sterol regulatory element-binding protein 1c (SREBP1c), stimulate the DNL, and trigger hepatic steatosis." (PMID 38089874, 2023). "Interestingly, we have showed that HApoD-Tsg mice develop a non-inflammatory hepatic steatosis during middle age due to an upregulation of PPARγ, which increases CD36 expression, and lipid droplet expansion." (PMID 37237893, 2023). "In this study, the expressions of cd36 mRNA were higher in mice fed on the HFD diet, despite white carrot or orange carrot supplementation, indicating that the increased hepatic uptake of FFA from the circulating system played a vital role in developing HFD-induced liver steatosis." (PMID 36225879, 2022). "After three days of starvation, the hepatic lipid droplets of WT zebrafish larvae increased significantly and the percentages of hepatic steatosis reached 92.12%, whereas the steatosis degree of cd36−/− mutants did not appear to have significant changes before and after starvation." (PMID 33513687, 2021). "Taken together these studies suggested that sCD36 could reflect hepatic steatosis, but did not demonstrate whether plasma sCD36 concentration correlates with the amount of intrahepatic fat as well as with the pattern of CD36 expression in the liver." (PMID 32978374, 2020). "Consequently, mice lacking Pcsk9 displayed hepatic steatosis features, including an elevation of CD36 protein levels although its mRNA content remained unchanged." (PMID 32978374, 2020). "Noteworthy, Cd36-knockout mice were also protected against a high-carbohydrate liquid diet-induced hepatic steatosis but by a distinct mechanism regardless of hepatic fatty acid uptake and related to decreased expression of genes in the de novo lipogenesis pathway." (PMID 32978374, 2020). "However, it has recently been shown that Cd36 is important in the regulation of very low density lipoprotein (VLDL) secretion in the liver, which may suggest a protective role against hepatic steatosis." (PMID 26151952, 2016). "Thus, myriocin induced improvement in dyslipidemia and hepatic steatosis in our study may also be related to changes in NPC1L1, CD36 and FATP4 expression and alterations in lipid raft composition that reduce intestinal fatty acid and cholesterol uptake." (PMID 25993337, 2015).
Hepatic steatosis (continued). "However, TUDCA did not reduce the expression of Pparg, which is a critical transcription factor in development of hepatic steatosis in ob/ob mice, and its direct target genes (e.g., Cidec, Cd36, and Ucp2), suggesting that the TUDCA effect in improving hepatic steatosis is Pparg-independent." (PMID 21079772, 2010). "Because the expression of CD36, DGAT2, and PLIN2 in liver is previously known to be regulated by PPARγ, a crucial nuclear transcription factor controlling cellular glucose and lipid metabolism, we also investigated whether PPARγ is involved in VPA-induced hepatic steatosis." (PMID 27034954, 2016). "As a result, liver TG contents, plasma TG, and hepatic FFA levels were reduced in CD36‐depleted mice in the presence of NR2F6 overexpression, suggesting that NR2F6 cannot promote liver steatosis in the absence of CD36." (PMID 33173745, 2020). "In contrast to what has been reported in human and mouse studies, the highly significant upregulation of PPARG, CD36, LPL, and FABP4 in the liver of the minipigs do not result in development of abundant hepatic steatosis." (PMID 32205840, 2020). "Our results show that Göttingen Minipigs do not develop abundant hepatic steatosis in spite of the significantly increased expression of PPARG, FABP4, CD36, and LPL in the liver." (PMID 32205840, 2020). "Therefore, we aimed to test an alternative approach that blocks glucocorticoid-induced fatty liver without compromising its beneficial action, given the fact that upregulation of FASN and CD36 is crucial in mediating glucocorticoid-induced fatty liver." (PMID 39820544, 2025). "This is suggesting that in elderly individuals with NAS, enhanced CD36 translocation may contribute to hepatic steatosis and NAFLD as opposed to absolute CD36 protein levels." (PMID 24751397, 2014).
Insulin resistance (185 papers, 2007 to 2025). Increased resistance towards insulin, that is, diminished effectiveness of insulin in reducing blood glucose levels. "CD36 is also implicated in lipid-induced insulin resistance and increased oxidized LDL uptake by monocytes, even in metabolically normal individuals." (PMID 40867895, 2025). "CD36, a fatty acid transporter enzyme in the liver, is linked to pathological conditions (visceral obesity, insulin resistance, and non‐alcoholic fatty liver disease [NAFLD])." (PMID 40612138, 2025). "MBV insulin resistance in CD36-deficient individuals is supported by findings in cultured hMECs where CD36 depletion impairs insulin signalling and eNOS activation." (PMID 39503770, 2025). "In humans, a CD36 SNP (rs1527479) associates with insulin resistance and type 2 diabetes and a mutation (rs56381858) associates with autosomal-dominant type 2 diabetes." (PMID 39503770, 2025). "It is known that increased CD36-mediated fatty acid uptake and lipid accumulation precede the loss of insulin-stimulated glucose uptake and the associated development of insulin resistance." (PMID 39125700, 2024). "CD36 is also associated with macrophage foam cell development in atheromatous plaque formation, insulin resistance, oxidative stress (i.e., ischemia-reperfusion injury), and apoptosis/autophagy mechanisms." (PMID 38790959, 2024). "In humans, CD36 deficiency has been associated with insulin resistance, and human CD36 deficiency or human CD36 variants have been associated with abnormal plasma lipid levels." (PMID 38716728, 2024). "Hepatic CD36 up-regulation has been significantly associated with insulin resistance and steatosis in NAFLD patients." (PMID 36410795, 2023). "During lipid overload, increased CD36-mediated FA uptake and lipid accumulation are known to precede the development of insulin resistance and the associated loss of insulin-stimulated glucose uptake." (PMID 36361698, 2022). "The CD36 gene has been strongly implicated in pathological conditions associated with metabolic dysregulation, such as insulin resistance and type 2 diabetes." (PMID 36031603, 2022). "CD36 deficiency in LECs highlights a novel mechanism for the etiology of visceral obesity and insulin resistance." (PMID 35992843, 2022). "Studies suggested that overexpression of CD36 can promotes the development of metabolic syndrome and insulin resistance, while CD36-deficient patients presented impaired glucose metabolism, insulin resistance and hyperlipidemia." (PMID 36213291, 2022). "Conversely, CD36 deficiency decreased insulin resistance in primary adipocytes isolated from HFD-fed mice." (PMID 34957117, 2021). "CD36 expression has been associated with insulin resistance in humans with type 2 diabetes and increased hepatic Cd36 gene expression was reported to increase fatty uptake, TAG accumulation and fatty liver." (PMID 33513874, 2021). "In fact, deficiency of human CD36 is frequently observed in Asian and African populations, and is linked to insulin resistance." (PMID 33854480, 2021). "The first complex-trait gene identified is the Cd36 gene, which causes insulin resistance, hyperlipidemia and hypertension in the spontaneously hypertensive rat (SHR)." (PMID 32741357, 2020). "In summary, HFD fed mice and palmitate-treated L6 skeletal muscle cells were used to explore the underlying molecular mechanisms of CD36 translocation to plasma membrane prior to insulin resistance." (PMID 31938068, 2020). "An increase in CD36 leads to increased uptake of fatty acids; this stimulates cytokine release and in vivo, associates with development of steatosis and systemic insulin resistance as well as inflammation in adipose tissue." (PMID 32971872, 2020).
Insulin resistance (continued). "CD36 deficiency is directly linked to insulin resistance and defective fatty acid metabolism in rats." (PMID 31547508, 2019). "It has previously been reported that insulin resistance was linked to increased protein expression of CD36." (PMID 30276217, 2018). "Clinical studies have shown that dysregulated expression of hepatic CD36 was significantly associated with insulin resistance, hyperinsulinemia, and increased steatosis in patients with NAFLD and chronic hepatitis C." (PMID 28770225, 2017). "We previously showed that Gpr40, also known as Ffar1, mediates high fat diet-induced hyperinsulinemia, and additionally our study suggested that hyperinsulinemia, hepatic Cd36 expression, hepatosteatosis, and insulin resistance were associated." (PMID 26085100, 2015). "Ezetimibe significantly reduced hepatic Cd36 gene expression, upregulation of which is significantly associated with insulin resistance, hyperinsulinemia and increased steatosis." (PMID 25310357, 2014). "One study revealed the association of CD36 deficiency with insulin resistance in patients with coronary heart diseases, while another study did not." (PMID 24016701, 2013). "Increased CD36 expression has been shown to contribute to dyslipidemia and to be associated with insulin resistance and decreased glucose tolerance, suggesting that CD36 is involved in the physiopathology of insulin sensitivity." (PMID 22662181, 2012). "Humans with CD36 deficiency exhibit hyperlipidemia, increased remnant lipoproteins, impaired glucose metabolism based upon insulin resistance, and mild hypertension." (PMID 21203512, 2010). "Thus, in CD36 deficiency, microvascular insulin resistance paradoxically associated with enhanced insulin sensitivity of glucose disposal." (PMID 39503770, 2025). "In humans, CD36 deficiency, which is relatively common (2%–7%) in persons of Asian and African descent, has been reported to exhibit insulin resistance, atherosclerotic heart disease, hyperlipidemia, and a propensity to develop NAFLD and atherosclerotic heart disease." (PMID 39774047, 2025). "CD36 has also been implicated in insulin resistance, which is linked to diabetes." (PMID 38584832, 2024). "CD36 gene is located on chromosome 7q11.2; mutations in CD36 gene are linked to abnormal plasma fatty acid and triglycerides, and metabolic disorders involving insulin resistance." (PMID 38583947, 2024). "In agreement with this hypothesis, we reported that ATM isolated from HFD-fed CD36 deficiency mice were protected from diet-induced pro-inflammatory signaling and insulin resistance." (PMID 39156133, 2024). "Surprisingly, increased CD36 has also being linked with insulin resistance through JNK." (PMID 36410795, 2023). "CD36 is also associated with insulin resistance via modulation of lipid uptake." (PMID 37711887, 2023). "Interestingly, Cd36 null mice exhibit elevated circulating LCFA and TG levels consistent with the phenotype of dKO mice and Cd36 deficiency partially protected from HFD-induced insulin resistance." (PMID 37603466, 2023). "However, our data are consistent with the association between Cd36 upregulation in the liver and insulin resistance, hyperinsulinemia, and steatosis, as well as with the induced increase in CD36 levels from inflammatory stress." (PMID 35883786, 2022). "High levels of fatty acids or lipid metabolites, especially oxidized low-density lipoprotein, can activate CD36+ cells and at the same time reversely inhibit insulin-associated glucose transporter-4, thereby inducing insulin resistance, which is defined as obesity-associated insulin resistance." (PMID 33628242, 2021). "Interestingly, in animal studies, a gene, the cd36 gene which encodes fatty acid translocase, appears to underlie insulin resistance, defective fatty acid metabolism and dyslipidemia in hypertension." (PMID 34394802, 2021).